MARCKSL1 (MARCKS like 1)
Diseases named in the same sentence as MARCKSL1 in open-access papers (continued):
Sharing a sentence is not in itself a finding about the gene and the disease.
tumor (17 papers, 2009 to 2025). "It has been reported that the lncRNA MARCKSL1-2 (MARCKSL1-transcript variant 2, NR_052852.1) promoted tumor progression by regulating epithelial–mesenchymal transition, thereby supporting the prognostic and therapeutic value of this lncRNA." (PMID 38473229, 2024). "MARCKS and MARCKSL1 are closely linked to tumor development, and part of the mechanism that has been clarified is immune-related, mainly in its widespread presence in innate immune cells and its involvement in the regulation of immune function." (PMID 37340044, 2023). "Additionally, MARCKSL1 is linked to tumour resistance to multiple anticancer drugs." (PMID 39944086, 2025). "Furthermore, MARCKSL1 was the strongest upregulated gene in response to estradiol in estrogen receptor alpha (ERα) positive cells co-cultured with bone cells; suggesting a more aggressive tumor phenotype associated with bone metastasis." (PMID 30856208, 2019). "MARCKSL1-positive (MARCKSL1(+)) expression was almost exclusively found in tumours with MVI, while MARCKSL1-negative (MARCKSL1(−)) expression lacked this specificity." (PMID 39944086, 2025). "The abundance of MARCKSL1 was correlated with tumour cell resistance to several drugs, including hypothemycin, vemurafenib, AP-26113, acrichine, erlotinib, and dabrafenib." (PMID 39944086, 2025). "These interactions are also specific to MARCKSL1(+), which functions as a receptor‒ligand pair and has been reported to be critical for tumour cell migration, particularly in interactions with vascular endothelial cells." (PMID 39944086, 2025). "These 6 tumor-exclusive proteins detected in every single sample comprised MARCKSL1, IKBIP, COPZ1, TIMP1, FAM50A and DPM3." (PMID 39681068, 2024). "The MARCKSL1 expression was compared with classical prognosticators such as age, tumor diameter, grade, hormone receptor status, presence of tumor-infiltrating lymphocytes (TILs) and proliferation, with distant metastases free survival as the endpoint." (PMID 30856208, 2019). "Key signaling molecules exclusively affected by tumor-priming include MAP2K3, MARCKSL1, STAT5A, and TNFAIP3, which are specifically associated with NK cell cytotoxicity against tumor targets." (PMID 31242243, 2019). "MARCKSL1 protein expression was significantly correlated to tumor size (Spearman’s rho 0.220, p = 0.007), Nottingham grade (rho 0.263, p = 0.002), MAI (rho 0.316, p <0.001), PPH3 (rho 0.317, p <0.001) and Ki-67 (rho = 0.269, p = 0.001)." (PMID 30856208, 2019). "The mechanistic studies via quantitative analysis of global proteome in xenograft tumours revealed that some metastasis-associated proteins, including S100A4, MARCKSL1 and BAG4 were increased in ELL(C595A) xenograft tumours compared to the control tumours." (PMID 27009366, 2016). "Among different prognosticators studied (age, tumor diameter, grade, estrogen receptor, and proliferation), MARCKSL1 protein expression was the strongest prognosticator." (PMID 27502506, 2016). "Moreover, MARCKSL1 protein levels were significantly increased in ESCC tumor tissues (n = 811) compared to adjacent esophageal epithelia (n = 442)." (PMID 35894387, 2023). "Furthermore, in vivo analysis using mouse xenograft tumor model supported that overexpression of MARCKSL1–2 attenuated the DTX resistance in LAD tumors." (PMID 35864549, 2022). "Additionally, in vivo study indicated that MARCKSL1–2 overexpression hindered tumor growth and strengthened the efficacy of DTX treatment in vivo." (PMID 35864549, 2022). "The role of MARCKSL1 in tumor progression thus remains to be elucidated." (PMID 30856208, 2019). "MARCKSL1 correlated significantly to tumor proliferation as measured by Ki-67, MAI and PPH3." (PMID 30856208, 2019).
tumor (continued). "It has been found that inflammatory factors cause a decrease in NK cell killing, while tumor cells cause an increase in NK cell killing, where the expression of several genes, including MARCKSL1, in NK cells is not affected by inflammatory factors and is only associated with exposure to tumor cells." (PMID 37340044, 2023). "Moreover, the level of MARCKSL1–2 in tumor tissues was lower than that in normal lung tissues." (PMID 35864549, 2022). "To further validate the significance of MARCKSL1–2 in DTX resistance in vivo, we constructed mouse models and observed the tumor growth in mice with different treatments." (PMID 35864549, 2022). "miR-140 also contributes to tumor suppressive effect by targeting COL4A1, ITGA6 and MARCKSL1 in breast cancer." (PMID 29162923, 2017). "The upregulations of S100A4, MARCKSL1, BCAM, BAG4, IPO4 and CPSF7 in pHAGE-ELL(C595A) tumours were confirmed." (PMID 27009366, 2016). "The expression of MARCKSL1 was significantly increased in ESCC tumor tissues (n = 811) compared to adjacent nontumorous tissues (n = 442)." (PMID 35894387, 2023). "In addition, MARCKSL1 was found to be significantly overexpressed in tumor tissues compared to adjacent nontumorous tissues." (PMID 35894387, 2023).
cardiovascular disease (1 paper, 2025). "In cardiovascular disease, endothelial polarity proteins like MARCKSL1 help establish endothelial identity and have atheroprotective effects." (PMID 40607379, 2025).
MARCKSL1 also shares sentences with these, for which no sentence is quoted: lung carcinoma (2 papers); autism (1); bacterial infection (1); bladder cancer (1); COVID-19 (1); depression (1); diabetes (1); endothelial dysfunction (1); gastric cancer (1); infection (1); leiomyosarcoma (1); liver cancer (1); liver tumor (1); meningioma (1); mycosis (1); neuroblastoma (1); pancreatic adenocarcinoma (1); Parkinson disease (1); rhabdomyosarcoma (1); spina bifida (1); uterine cancer (1).